TRPC5 (transient receptor potential cation channel subfamily C member 5)
Diseases named in the same sentence as TRPC5 in open-access papers (continued):
Sharing a sentence is not in itself a finding about the gene and the disease.
Arthritis (8 papers, 2017 to 2025). Inflammation of a joint. "Collectively, the results were in agreement with our mouse model of CFA-induced arthritis, revealing an association between TRPC5 expression and joint inflammation." (PMID 27165180, 2017). "TRPC5 channels have also been implicated in arthritis, although their role is unclear." (PMID 29865154, 2018). "The elevated concentrations of LPC-induced TRPC5-dependent neuronal activity in CFA-induced arthritis." (PMID 36926330, 2023). "This was in accordance with previous data from this laboratory that showed that TRPC5 expression had a protective role in inflammation- and pain-related behaviour, secondary to the development of experimental arthritis." (PMID 34203675, 2021). "Recently, we found that the deletion of TRPC5 leads to increased inflammation and pain-related behaviour in two animal models of arthritis." (PMID 34203675, 2021). "In comparison with the pronociceptive action of other TRPC proteins, TRPC5 is recently reported to be able to protect against pain and vascular inflammation in arthritis and joint inflammation." (PMID 32273889, 2020). "We show that deletion of TRPC5 resulted in an unexpected, neutrophil-driven inflammation 14 days following induction of arthritis." (PMID 27165180, 2017). "Transient receptor potential canonical 5 (TRPC5) is functionally expressed on a range of cells including fibroblast-like synoviocytes, which play an important role in arthritis." (PMID 27165180, 2017). "We assessed joint swelling by measuring thickness following CFA-induced arthritis and observed a significant increase by day 7 in both WT and TRPC5 KO mice; however, swelling was augmented in TRPC5 KO mice on day 14 compared with WT mice (p<0.05)." (PMID 27165180, 2017). "We examined the mRNA expression of TRPC5 in the mouse synovium 14 days following CFA-induced arthritis and observed a significant reduction in the expression of TRPC5 in the ipsilateral synovium compared with the contralateral synovium in WT mice (p<0.01)." (PMID 27165180, 2017). "We provide evidence that TRPC5 is protective in a murine model of arthritis, where genetic deletion/pharmacological blockade of TRPC5 sustained active joint inflammation, augmented hyperalgesia and synovitis." (PMID 27165180, 2017). "In the present study, we investigated the in vivo contribution of TRPC5 to the local inflammatory changes that occur in arthritis using pharmacogenomic approaches." (PMID 27165180, 2017). "Male wild-type and TRPC5 knockout (KO) mice were used in a complete Freund's adjuvant (CFA)-induced unilateral arthritis model, assessed over 14 days." (PMID 27165180, 2017). "Following CFA-induced arthritis, bilateral thermal hyperalgesia was observed in both groups with augmented ipsilateral hyperalgesia in TRPC5 KO mice (p<0.05)." (PMID 27165180, 2017). "Additionally, treatment with ML204 has been discovered to augment synovial inflammation and vascular swelling in CFA‐induced arthritis, indicating potential anti‐inflammatory functions of TRPC5." (PMID 40787071, 2025). "TRPC5 channels may also contribute to nociceptive signaling because TRPC5 KO mice exhibit reduced nociceptive thresholds (thermal and mechanical) in a complete Freund’s adjuvant-induced unilateral arthritis model." (PMID 32872338, 2020). "Whether pharmacological activation of TRPC5 is beneficial in arthritis is as yet unknown, but these results suggest a potentially protective role for TRPC5." (PMID 29865154, 2018). "We investigated the mRNA expression of inflammatory mediators in the synovium 14 days following CFA-induced arthritis and observed a significant induction in the expression of the nuclear transcription factor kappa B in the ipsilateral synovium of TRPC5 KO mice." (PMID 27165180, 2017). "Thus, we investigated the mRNA expression of TRPC5 and demonstrated a reduction in inflamed human arthritis samples." (PMID 27165180, 2017).
Arthritis (continued). "CFA-induced arthritis resulted in increased synovitis in TRPC5 KO mice assessed by histology." (PMID 27165180, 2017). "Human fibroblast-like synoviocytes, the cells that secrete synovial fluid, express TRPC1 and TRPC5, and blocking their activity using antibodies or siRNA increases the secretion of matrix metalloproteases (MMPs), which is thought to lead to tissue remodelling and arthritis." (PMID 29865154, 2018). "The role of TNFα in inflammatory hyperalgesia is fundamental; we detected abundant expression of TNFα mRNA in the inflamed synovium of both TRPC5 WT and KO mice, 14 days following CFA-induced arthritis." (PMID 27165180, 2017). "Mice lacking RPC5 or treated with the TRPC5 antagonist ML204 have shown an increase in hyperalgesia during CFA‐induced arthritis." (PMID 40787071, 2025). "In summary, the current data suggests that agonism of TRPC5, TRPM3, TRPM8, and TRPV2 may help ameliorate or prevent arthritis, while antagonism of TRPM7 and TRPV4 may have a similar effect." (PMID 30326593, 2018). "At day 14 following CFA-induced arthritis in WT and TRPC5 KO mice, we observed no significant change in blood flow of the ipsilateral synovium of TRPC5 WT mice compared with the contralateral synovium." (PMID 27165180, 2017). "Additionally, TRPC5 KO mice demonstrated reduced ispilateral weightbearing and nociceptive thresholds (thermal and mechanical) following CFA-induced arthritis." (PMID 27165180, 2017). "However, the expression of the T cell marker, cluster of differentiation 3, was significantly increased in both TRPC5 WT and KO mice highlighting increased infiltration of lymphocytes following CFA-induced arthritis." (PMID 27165180, 2017). "Additionally, TRPC5 channel expression is increased in the synovium in a mouse model of arthritis, and genetic deletion of TRPC5 as well as pharmacological inhibition with ML204 exacerbate arthritis induced by injection of complete Freud’s adjuvant." (PMID 29865154, 2018).
glomerular diseases (7 papers, 2016 to 2025). "Consistent with an important role for TRPC5 in glomerular diseases, inhibition of TRPC5 ameliorated glomerular injury in proteinuric rodent models." (PMID 35991898, 2022). "While the role of TRPC6 in several proteinuric kidney diseases is well‐established, the role of TRPC5 in glomerular disease is currently being discussed." (PMID 34042270, 2021). "Despite these promising findings, the role of TRPC5 in glomerular disease processes is controversial." (PMID 31877991, 2019). "Consistent with an important role for TRPC5 in glomerular diseases, additional studies by this same group suggested that inhibition of TRPC5 ameliorated glomerular injury in proteinuric rodent models, as discussed further below." (PMID 31877991, 2019). "Other members of the TRPC family have effects on glomerular diseases, such as TRPC5 and TRPC3." (PMID 35991898, 2022). "In the glomerular disease models that we previously examined, we found that TRPC5 abundance neither increased nor decreased relative to what was seen in control animals, and we do not know the mechanisms leading to loss of TRPC5 in protein overload." (PMID 35805070, 2022). "The mechanism(s) of enhanced TRPC5 activity in this model was not further investigated in this published study, but changes in the level of TRPC5 expression in the kidney have not been observed in animal models of glomerular disease." (PMID 31877991, 2019). "An important observation was that TRPC3 is upregulated in glomerular diseases in a fashion similar to TRPC6, with no change in expression of TRPC5." (PMID 31877991, 2019).
Obesity (7 papers, 2019 to 2025). Accumulation of substantial excess body fat. "The hyperphagia is also partially mediated by impaired Trpc5 actions on OXT neurons in the PVH as deletion from this site caused hyperphagic obesity, which was reversed by OXT supplementation." (PMID 38959890, 2024). "Deletion of Trpc5 from oxytocin neurons in the hypothalamic paraventricular nucleus caused obesity in both sexes and postpartum depressive behavior in females, while Trpc5 overexpression in oxytocin neurons in knock-in mice reversed these phenotypes." (PMID 38959890, 2024). "Disruption of TRPC5, a brain-expressed cation channel, causes obesity, maladaptive behavior, and postpartum depression in humans and mice." (PMID 38959890, 2024). "Nonetheless, the use of TRPC4/TRPC5 inhibitors for cosmetic weight loss as well as to combat obesity, T2D, MS, NAFLD and non-alcoholic steatohepatitis was recently published (accession numbers: WO/2018/146485; EP3579838; US20200345741)." (PMID 35455971, 2022). "In fact, the neuronal deficiency of TRPC5 or its deletion in pro-opiomelanocortin neurones leads to obesity associated with decreased energy expenditure and higher food intake in mice." (PMID 35455971, 2022). "Similarly, recent studies have identified transient receptor potential channel 5 (TRPC5) as a significant contributor to obesity and associated behavioral phenotypes by identifying microdeletions on chromosome Xq23 encompassing this gene." (PMID 39237720, 2025). "To investigate whether mutations in TRPC5 cause obesity and the behavioral phenotypes we observed, we generated a knockin mouse model of a human severe LoF mutation, K34del (Trpc5K34del mouse line)." (PMID 38959890, 2024). "There were far fewer male carriers of TRPC5 variants in UK Biobank (88 men compared with 281 women), possibly because people with severe obesity and/or complex behavioral phenotypes may be less likely to volunteer for research studies." (PMID 38959890, 2024). "Supplementation of OXT in male and female OXT-Trpc5-KO mice reduced food intake and body weight to levels comparable to WT mice, suggesting that OXT analogs/receptor agonists could be effective in treating human obesity due to TRPC5 deficiency." (PMID 38959890, 2024). "The deletion of transient receptor potential channel 5 (Trpc5) in oxytocin neurons of the hypothalamic paraventricular nucleus leads to obesity and postnatal depressive behaviors in female mice, whereas overexpression of Trpc5 reverses these phenotypes." (PMID 40001206, 2025). "Both probands had brothers who had severe obesity and carried TRPC5 deletions, which were from their mothers who also had obesity." (PMID 38959890, 2024). "Using comparative genomic hybridization, we identified microdeletions on chromosome Xq23 disrupting TRPC5 in two boys with severe obesity from unrelated families of European ancestry in whom known genetic causes of obesity had been excluded." (PMID 38959890, 2024). "Our study fills an important gap in the knowledge about EDC under disease conditions, and lays out a blueprint for the future development of TRPC5-based therapeutic options against obesity." (PMID 38933403, 2022). "We then investigated the involvement of COX in the TRPC5-cPLA2-regulated vasocontraction in obesity." (PMID 38933403, 2022). "The role of the Ca2+-permeable ion channel TRPC5 in regulating vasocontraction in obesity is poorly understood." (PMID 38933403, 2022). "We demonstrated that increased TRPC5 expression in obesity augmented the EDC response, which further promoted endothelial dysfunction." (PMID 38933403, 2022). "Our study suggested that the balance between vasodilator and vasoconstrictor metabolites of arachidonic acid is disturbed in obesity and is regulated by increased TRPC5 and activated cPLA2." (PMID 38933403, 2022). "In sum, this study demonstrated that TRPC5 plays a role in vascular dysfunction in obesity by enhancing EDC in the DIO mouse aorta via activation of cytosolic cPLA2 in endothelial cells." (PMID 38933403, 2022).
Obesity (continued). "In addition to non-clinical studies, the beneficial effects of modulating TRPV1, TRPA1 and TRPC5 channels in obesity, T2D, atherosclerosis and MS have been investigated in a range of clinical trials." (PMID 35455971, 2022). "Although endothelial TRPC5 has been shown to contribute to contraction in mouse carotid artery, its role in vascular tone control under pathophysiological conditions such as obesity remained elusive." (PMID 38933403, 2022). "TRPC5 knockout and inhibition alleviated the endothelial dysfunction induced by obesity." (PMID 38933403, 2022). "Here, we investigated whether TRPC5 contributes to vascular dysfunction in obesity by promoting endothelium-dependent contraction via activation of cytosolic phospholipase A2 (cPLA2) in the aortic endothelial cells of obese mice." (PMID 38933403, 2022). "In the present study, we hypothesized that TRPC5 contributes to vascular dysfunction in obesity by promoting EDC." (PMID 38933403, 2022). "Interestingly, the obesity seen in mice lacking Trpc5 in PVH OXT neurons was more severe than in the Trpc5K34del knockin mouse model." (PMID 38959890, 2024). "Experiments in TSE PhenoMaster metabolic cages confirmed increased food intake and decreased locomotor activity but no change in energy expenditure (using body mass as a covariate), indicating that hyperphagia is the major driver of obesity in mice lacking Trpc5 in OXT neurons." (PMID 38959890, 2024). "Despite the mechanism being unknown, our observation of significant reduction in body weight without obvious adverse effect indicates that targeting TRPC5 channels is a potential way to reduce obesity in the context of hypercholesterolaemia." (PMID 30692584, 2019).
depression (6 papers, 2017 to 2026). "TRPC5 mediates diverse physiological processes and is implicated in many disease conditions in human such as fear, anxiety, depression, and progressive kidney disease." (PMID 33683200, 2021). "Overexpression of Trpc5 in PVH OXT neurons in Trpc5K34del/+ mutant dams ameliorated maternal depression-like behavior." (PMID 38959890, 2024). "TRPC5 inhibitors show promise in the treatment of anxiety disorder, depression, and kidney disease." (PMID 33683200, 2021).
epilepsy (5 papers, 2018 to 2021). A brain disorder characterized by episodes of abnormally increased neuronal discharge resulting in transient episodes of sensory or motor neurological dysfunction, or psychic dysfunction. "TRPC4 and TRPC5 channels are expressed in the central nervous system where their activation has been associated with epilepsy and fear." (PMID 30038709, 2018). "As first reported in 1995, TRPC1 protein can interact with TRPC4 and TRPC5 to form TRPC1/4/5 channels, which are significantly implicated in epilepsy." (PMID 34697589, 2021). "It is reported that the TRPC5 channel is similarly activated after epilepsy, resulting in an increase in neuronal death in the hippocampus." (PMID 33158109, 2020). "TRPC5 KO mice showed decreased excitability during epilepsy and reduced normal spatial learning, and also showed a reduction of neuronal death." (PMID 33158109, 2020). "The time course of increase in Ca2+ suggests that inhibitors of TRPC5 have neuroprotective effects even when administered at later stages of acute neuronal injuries, such as epilepsy." (PMID 30062674, 2019). "However, in previous studies it has been shown that NU6027 inhibits TRPC5 activity in channels present in cortical neurons that are activated during epilepsy, reducing calcium influx." (PMID 33158109, 2020). "NU6027 also reduced H2O2 increase in cortical neurons during epilepsy, indicating that NU6027 has reduced the activity of TRPC5 channels, ultimately reducing neuronal death." (PMID 33158109, 2020). "Moreover, in pilocarpine-induced epilepsy, TRPC4/TRPC5 blockade significantly inhibits seizure severity." (PMID 34489621, 2021).
glioma (5 papers, 2020 to 2024). A benign or malignant brain and spinal cord tumor that arises from glial cells (astrocytes, oligodendrocytes, ependymal cells). "Higher levels of TRPC1, TRPC3, and TRPC5 were significantly associated with longer OS time in glioma." (PMID 35625048, 2022). "Among the eight final identified hub genes, higher expression levels of TRPC1, TRPC3, and TRPC5 were significantly associated with longer OS time in glioma, while higher expression levels of TRPC4, TRPC6, MCOLN1, MCOLN2, MCOLN3 were significantly associated with shorter OS time." (PMID 35625048, 2022). "Furthermore, prednisolone, largely used in the context of glioma treatment to decrease glioblastoma-associated edema, also acts as a weak activator of TRPC5." (PMID 34458247, 2021). "The gene expression levels of TRPC1, TRPC3, and TRPC5 were significantly higher in low-grade glioma (LGG), while the levels of TRPC4, TRPC6, TRPM7, MCOLN1, MCOLN2, and MCOLN3 were significantly higher in high-grade glioma (HGG)." (PMID 35625048, 2022). "The results of the spheroid model showed that the genes TRPC3, TRPC4, TRPC5, and TRPV1 were upregulated in glioma cells either wild‐type isocitrate dehydrogenase 1 (IDH1) or the IDH1 R132H mutant, with or without NaCl treatment." (PMID 39189437, 2024). "Consistent expression of TRPC1, TRPC3, TRPC5, and TRPC6 has been found in glioma cell lines and acute patient-derived tissues, which gives rise to small, nonvoltage-dependent cation currents and contributes to the resting conductance of glioma cells." (PMID 32963700, 2020).
Huntington disease (5 papers, 2018 to 2024). Huntington disease (HD) is a rare neurodegenerative disorder of the central nervous system characterized by unwanted choreatic movements, behavioral and psychiatric disturbances and dementia. "In Huntington’s disease cell lines, increased calcium influx through TRPC5 causes cell death, whereas, in wild-type cell lines, calcium influx through TRPC5 was reduced when both TRPC1 and TRPC5 formed a heteromeric complex." (PMID 39000357, 2024). "This study exploited the S-glutathionylation of TRPC5 that responds to oxidative stress and underlined its importance in the pathogenesis of Huntington’s disease." (PMID 31936014, 2020). "In the striatum of both transgenic mice and patients with Huntington’s disease, increased glutathionylated-TRPC5 level was detected; this was suggested to underlie the neurodegeneration in Huntington’s disease." (PMID 31936014, 2020). "In the Huntington’s disease model, activation of TRPC5 through glutathionylation has also been shown to cause the loss of striatal neurons, and this effect can be mitigated through destabilizing the presence of TRPC5 on plasma membrane via depalmitoylation." (PMID 33490083, 2020). "Low levels of TRPC1 increased the formation of homotetrameric TRPC5, a highly Ca2+-permeable channel, and stimulated Ca2+-dependent apoptosis in Huntington’s disease cells." (PMID 30108272, 2018). "Moreover, application of a TRPC5 inhibitor in Huntington’s disease transgenic mice improved their rearing behavior." (PMID 31936014, 2020).